CBX7 (chromobox 7)
Diseases named in the same sentence as CBX7 in open-access papers (continued):
Sharing a sentence is not in itself a finding about the gene and the disease.
cancer (continued). "Multiple studies have revealed that CBX7 may have diverse roles in different cancer types." (PMID 28030829, 2017). "Summarizing the inferred partial correlation (or direct influence) networks for each cancer type across all cancers predicts that overexpression of UHRF1 and WHSC1 and underexpression of CBX7 could be key drivers of cancer DNA hypermethylation and DNA hypomethylation, respectively." (PMID 26169266, 2015). "Contribution of CBX7 to cancer development may be organ-dependent." (PMID 25881303, 2015). "Therefore, because the CC patients were much older than the controls, the Cbx7 mRNA level in the normal colon tissues distant from the site of malignancy (not available in the present study) should be lower than that from the non-cancer controls." (PMID 25881303, 2015). "In other words, the expected Cbx7 expression difference between the SMs and distant normal colon from the CC patients might be higher than the observed difference between the SMs and normal colon biopsies from non-cancer patients." (PMID 25881303, 2015). "In addition, the CC tissues revealed strong CBX7 protein expression in the nucleus of cancer cells." (PMID 25881303, 2015). "However, nuclear CBX7 staining was more prevalent in the glandular epithelial cells and stromal lymphoid cells in the corresponding SMs as well as normal colon biopsies from non-cancer patient controls." (PMID 25881303, 2015). "Indeed, these mice develop liver and lung adenomas and carcinomas, and accordingly, mouse embryonic fibroblasts (MEFs) derived from Cbx7-knockout (KO) embryos have a higher growth rate and a reduced susceptibility to senescence than their wild-type (WT) counterparts." (PMID 25190058, 2014). "The opposite role of CBX7 in different studies may be due to the different cancer types." (PMID 20723236, 2010). "The opposite expression level of CBX7 in different studies may due to the different cancer types." (PMID 20723236, 2010). "As CBX7 is capable of regulating cellular proliferation and senescence, and CBX7 expression is downregulated during replicative senescence, the results suggest that cancer cells in aged person might have lower proliferative ability, or more cells in aged person are in the senescent state." (PMID 20723236, 2010). "Of note, It was revealed that the expression of most genes was generally consistent with results of TCGA cancer set, such as TRIM24, HMG20B, CBX6, IDH1, RCC1, RYBP, CBX7, and LBR." (PMID 36246611, 2022). "Instead, CBX7 can up-regulate the expression of FOS, FOSB, and EGR1, which are mostly involved in the physiological process of inhibiting cancer." (PMID 34659360, 2021). "In addition, CBX7 protein may interact with different RNAs (microRNAs, long noncoding RNAs, circular RNAs) in different cancer environments to participate in a variety of pathways, affecting the development of cancers." (PMID 34659360, 2021). "For example, CBX7 positively regulated E-cadherin expression by inhibiting HDAC2 and PRMT1 activity on the E-cadherin promoter, and thereby suppressed cancer progression." (PMID 34035231, 2021). "CBX paralogs are frequently misregulated in cancer, with CBX2 and CBX8 as the most commonly upregulated paralogs, and CBX7 and CBX6 as the most commonly downregulated." (PMID 34617019, 2021). "The ectopic expression of CBX7 suppressed UBC cell proliferation, migration, invasion, and cancer stemness, whereas CBX7 depletion promoted cancer cell aggressiveness." (PMID 34035231, 2021). "Next, we identified a downstream target gene of CBX7, which drives MAPK signaling pathway to facilitate cancer progression." (PMID 34035231, 2021). "Based on the genomic expression data in the whole cancer population, the top prognostic genes were identified, such as FOXM1, CBX7, CREBL2 and SKP2, which were consistent with previous studies." (PMID 27322207, 2016).
cancer (continued). "Among the genes that appeared down-regulated by CBX7 expression we focused on the SPP1, SPINK1 and STEAP1 genes since their expression has been found overexpressed in human carcinomas." (PMID 24865347, 2014). "The 5-year OS rate of patients with negative expression of CBX7 was lower than that reported by the American Cancer Society (66% for CC)." (PMID 33748425, 2021). "It needs to be pointed out that different RNA molecules have a complex relationship with CBX7, forming an intricate network between them, making the effect of CBX7 on cancer is not absolute." (PMID 34659360, 2021). "CBX7 overexpression also resulted in reduced ZEB1 expression, a downstream target of the Wnt/β-catenin pathway and a classical EMT regulator in many types of cancer." (PMID 28388562, 2017). "We integrated known CBX7 targets with genes upregulated following CBX7 knockdown in LNCaP cells from the microarray analysis (E-MTAB-3730) and found activation of prominent cancer pathways such as epithelial to mesenchymal transition (EMT) and Wnt/β-catenin signaling pathways." (PMID 27449098, 2016). "Thus, these cancer cell lines MGC803, BGC823 (p16-active and low level of CBX7 expression), and PC3 (p16-methylated and high level of CBX7 expression) were used as the representative cell lines in the subsequent experiments." (PMID 21060834, 2010). "On the other hand, CBX7 expression negatively correlates with genomic alterations, especially in LUAD and PAAD tumors, which corresponds to the negative association between CBX7 and cancer stemness." (PMID 36361869, 2022). "Notably, compared with overexpression of RNF26 alone, overexpression of RNF26 in CBX7 knockdown cells did not further increase cancer cell growth." (PMID 35342353, 2022). "While many cancer-specific alterations in PcG subunits are related to specific developmental pathways or cancer-specific phenotypes, some sets of paralogs are universally up and downregulated across multiple cancers, including EZH2/EZH1, RING1B/RING1A and (CBX2/CBX8)/(CBX6/CBX7)." (PMID 34617019, 2021). "Therefore, we hypothesized that miR-375 might regulate the sensitive and dynamic equilibrium of CBX7 and CBX8 expression, which is known to impact transcriptional programs in development and cancer." (PMID 27449098, 2016). "The role that CBX7 exerts in cancer is still controversial and not defined at all." (PMID 25595895, 2015). "The role of CBX7 in most types of cancer is still not clear." (PMID 20723236, 2010). "Additionally, western blot and RT-qPCR analysis confirmed the positive regulation of CBX7 and IGF-1R on cancer stem cell markers CD133 and CD44, rescuing the negative influence of FOXC1 knockdown on these markers." (PMID 38413558, 2024). "Therefore, the absence of CBX7 would negatively regulate the SPP1 gene expression through HMGA1b, thus reducing the E-cad, inducing the EMT, and eventually promoting the cancer progression." (PMID 33748425, 2021).
infection (4 papers, 2012 to 2024). The state of being infected such as from the introduction of a foreign agent such as serum, vaccine, antigenic substance or organism. "Similar results were obtained upon infection of Cbx7-EGFP ESCs with retroviral vectors expressing miR-125b or miR-181a/b." (PMID 22226354, 2012). "Consistent with a Cbx7-mediated phenotype, infection with the pLKO-shCbx7.1 lentivirus resulted in differentiation of control ESCs but not of Cbx7-EGFP-expressing ESCs." (PMID 22226354, 2012). "Likewise, infection with CBX7-siRNA lentivirus significantly reduced CBX7 in Panc-1 and MIA PaCa-2 cells, compared with cells infected with control virus." (PMID 28030829, 2017).
CBX7 also shares sentences with these, for which no sentence is quoted: acute lymphoblastic leukemia (2 papers); gastric adenocarcinoma (2); mesothelioma (2); bacterial infections (1); bladder transitional cell carcinoma (1); brain tumor (1); central serous chorioretinopathy (1); diabetes (1); endometrial cancer (1); ependymoma (1); hematological malignancies (1); lentivirus infection (1); lung squamous cell carcinoma (1); malignant glioma (1); myeloma (1); nasopharyngeal carcinoma (1); rectal cancer (1); skin cancer (1); T-cell lymphoma (1).